IL1B (interleukin 1 beta)
Diseases named in the same sentence as IL1B in open-access papers (continued):
Sharing a sentence is not in itself a finding about the gene and the disease.
mental disorder (13 papers, 2011 to 2025). A disease that has its basis in the disruption of mental process. "Recent studies have shown that proinflammatory cytokines, such as interleukin-1 beta (IL-1β), induced by stress, initiate the neuroinflammatory processes producing the physiological and behavioral responses associated with mental disorders." (PMID 34884503, 2021). "A meta-analysis revealed considerably higher concentrations of IL-1β and IL-6 in blood and postmortem brain samples of individuals with mental disorders who had attempted suicide." (PMID 41035953, 2025). "There have been many reports that IL-1β plays a central role in mediating DM, cardiovascular diseases, and progression of mental disorders." (PMID 37251380, 2023). "This surprising finding was confirmed after including BMI as a cofactor for the statistical analysis of IL-1β mRNA levels in obese patients according to the presence of mental disorders." (PMID 30504920, 2018). "On the other hand, S100-βactivates inflammatory pathways, stimulating microglia and astrocytes to releasepro-inflammatory cytokines, such as tumor necrosis factor-α(TNF-α) and interleukin-1β (IL-1β), further exacerbatingneuroinflammation and contributing to the onset of mental disorders." (PMID 39801405, 2025). "IL-1β treatment elicits depressive-like behaviors, neuroprogression, and inflammation, and IL-1β antagonists were suggested to play antidepressant roles in several mental disorders." (PMID 31736656, 2019). "Also, cytokines like IL-1β and IL-6 were detected at statistically significant levels in the cardiovascular disease group and all cytokines included in this study were quantified in the mental disorders group." (PMID 39328992, 2024). "Additionally, IL1B rs16944 was associated with development of CP after HIE in a previous study, consistent with our results, and also various other diseases, including mental disorders." (PMID 34573127, 2021). "Subsequently, we examined how immune-mediated classes were reflected in leukocyte counts, inflammatory markers (IL-1β, IL-6, TNF-α, hsCRP), chronic inflammatory diseases, and mental disorders, and how they differed across social classes and birth cohorts." (PMID 30961604, 2019). "Regarding obese patients, the relationship between inflammatory markers and mental disorders was no observed, with the exception of IL-1β." (PMID 30504920, 2018).
monocytic leukemia (13 papers, 2013 to 2025). "For instance, silver carp bone hydrolysate lowered the levels of tumor necrosis factor-alpha (TNF-α) and interleukin-1 beta (IL-1β), two key mediators of the inflammatory response in LPS-treated human monocytic leukemia cells." (PMID 41009001, 2025). "In the human monocytic leukemia cell line THP-1, used for inflammasome/pyroptosis studies, CLM increased release of IL-1β and active caspase-1 (compared with ATP) already 3 hours after activation (respectively)." (PMID 40371642, 2025). "DHA inhibits the inflammatory cytokines, such as IL-6, and TNF-α and IL-1β expression induced by LPS in THP-1 cells, which is the human monocytic leukemia cell line." (PMID 36741381, 2022). "It has been previously reported that IL-1β induces both TIMP-1 and MMP-9 in monocytes and monocytic leukemia cells." (PMID 23967215, 2013). "The amount of IL-1β and TNF-α mRNA expressed in a human monocytic leukemia cell line (THP-1) is visualized and counted using single-molecule fluorescent in-situ hybridization (smFISH) following exposure of the cells to lipopolysaccharide (LPS), an outer-membrane component of Gram-negative bacteria." (PMID 34211022, 2021). "None of the strains could invade macrophages, although incubation of the C. showae strains with the THP-1 human monocytic leukemia cell line for 6 h led to proinflammatory cytokine production (TNF-α, IL-1b and IL-8)." (PMID 31169073, 2019). "In particular, menadione inhibited nuclear factor kappa-light-chain-enhancer of activated B cell (NF-κB) activation and thereby reduced expression of the proinflammatory cytokines such as IL-1β, IL-6, IL-8, and TNF-α in AGS as well as in THP-1 (monocytic leukemia cell) cell lines." (PMID 30866458, 2019). "Our results on the biological activities of RCAs in the matrix of bacterial cellulose showed that there was low-level LDH activity/cytotoxicity towards the monocytic leukemia cell line THP-1, as well as an absence of proinflammatory cytokine boosting, e.g., IL-1β, characteristic of pyroptosis." (PMID 40808164, 2025).
renal failure (13 papers, 2016 to 2025). "These metabolites significantly inhibit the expression and release of inflammatory cytokines (e.g., TNF-α, IL-1β, and IL-6) induced by podocyte injury, which helps improve renal insufficiency caused by podocyte dysfunction and prevents renal parenchymal damage." (PMID 41194878, 2025).
spinal cord injury (13 papers, 2014 to 2024). Penetrating and non-penetrating injuries to the spinal cord resulting from traumatic external forces (e.g., WOUNDS, GUNSHOT; WHIPLASH INJURIES; etc.). "In the case of spinal cord injuries, inflammasome activation mediates the inflammatory response through IL-18 and IL-1β with the activation of T helper lymphocytes (LTh1)." (PMID 36826052, 2023). "At the same time, the expression of AKT1 gene decreased, the results suggested that the increase of IL-1β affected the functional recovery of spinal cord contusion." (PMID 39262872, 2022). "Interleukin-1β (IL-1β) is a key inflammatory factor that promotes the aggravation of spinal cord contusion." (PMID 39262872, 2022). "Studies have found that miR-223 and the inflammatory factors TNF-α, IL-1β, and IL-6 were highly expressed in the lesions of acute spinal cord injury in mice, which reached the maximum peak at 12–24 h after injury." (PMID 32295141, 2020). "Meanwhile, pro-inflammatory cytokine production (such as TNF-α and IL-1β) and iNOS expression were significantly decreased after administration of oleuropein aglycone in spinal cord trauma." (PMID 24842137, 2014). "Therefore, IL-1β mediated early inflammation is rapid and extensive and plays an important role in the acute phase of spinal cord contusion." (PMID 39262872, 2022). "Another study demonstrated that Tan IIA could reduce the levels of IL-6, TNF-α and IL-1β by markedly inhibiting the activation of NF-κB and the mitogen-activated protein kinases (MAPKs) pathways in a spinal cord injury model." (PMID 25157742, 2014). "It has been suggested that TMEM176A and TMEM176B inhibit the maturation and activation of dendritic cells in chronic spinal cord injury and that TMEM176B impairs IL-1β secretion and reduces CD8+ T cell-dependent antitumor immunity." (PMID 39684780, 2024). "Inhibiting the expression and activation of both metal matrix proteinase (MMP)-2 and MMP-9 after spinal cord injury (SCI) and the mRNA expressions of TNF-α, IL-1β, COX-2, and iNOS." (PMID 27951737, 2017). "Moreover, after lentiviral interference with IL-1β, the expression of AKT1 increased and PI3K expression remained unchanged, and motor function was significantly restored in rats with spinal cord contusion." (PMID 39262872, 2022). "For instance, an animal model of spinal cord injury (SCI), EA has shown neuroprotective effects by reducing levels of microglial and proinflammatory mediators, such as precursor pro-nerve growth factor and proinflammatory cytokines (TNF-α, IL-1β, and IL-6)." (PMID 32283868, 2020). "In conclusion, IL-1β may affect neuronal apoptosis and regeneration through the regulation of mTOR, FOXO, and GSK3 expression via the PTEN/AKT1 signaling pathway, thereby affecting neuronal survival and functional recovery after spinal cord contusion." (PMID 39262872, 2022). "For instance, Yang and colleagues demonstrated that a contused model of spinal cord injury (SCI) in mApoE-knockout mice led to an exaggerated inflammatory response with increased expression of nuclear factor κB (NF-κB) and cytokine levels such as IL-6 and IL-1β." (PMID 34369386, 2021). "The experimental results showed that interfering with IL-1β can upregulate the expression of AKT1, thereby affecting the functional recovery of spinal cord contusion, but PI3K is not affected by IL-1β." (PMID 39262872, 2022).
staphylococcus aureus infection (13 papers, 2013 to 2025). An infectious process in which the bacteria Staphylococcus aureus is present. "The systemic administration of IL-1β has been shown to compensate its deficiency in skin lesions of Il-1β−/− mice, induced by Staphylococcus aureus infection." (PMID 24312491, 2013). "In the early stages of Staphylococcus aureus infection, the expression levels of several genes encoding pro-inflammatory molecules (IL8, IL1B, OSM, and CXCR1, etc.)show a dramatic increase, with the expression of IL8 increasing up to 8196-fold." (PMID 39065061, 2024). "The secretion of IL-1β has been reported to be influenced by several stimuli, such as nigericin and maitotoxin, as well as Staphylococcus aureus infection." (PMID 37238962, 2023). "On the contrary, soluble uric acid effect during Staphylococcus aureus infection induced larger autophagy flux in macrophages but significantly less IL-1β release." (PMID 33322651, 2020). "IL-1β and reactive oxygen species (ROS) secreted by phagocytes are important factors that protect against Staphylococcus aureus infection." (PMID 29667111, 2018). "Moreover, AP-1 directly regulates the transcription of inflammatory mediators (TNF-α, IL-2, IL-12, IL-1β, IL-8) and their receptors (IL-2R) in the cytokine–cytokine receptor interaction and Staphylococcus aureus infection pathways." (PMID 40647090, 2025). "This anti-inflammatory effect could also be demonstrated in Wistar rats with induced peritoneal Staphylococcus aureus infection: Aloe gel extract alone increased the liberation of IL-1β and, as expected, infected animals exhibited increased IL-1β-levels." (PMID 30941196, 2019). "Staphylococcus aureus infection induces severe inflammation, which leads to significant upregulation of TNF-α, IL-1β, and IL-6 in both lung tissues and cells." (PMID 38803378, 2024). "Staphylococcus aureus infection triggers early cytokine secretion, such as TNF-α, IL-1β, and IL-6, which promotes the inflammatory response and recruits other immune cells to combat invading microorganisms." (PMID 35935196, 2022).
cognitive disorder (12 papers, 2017 to 2026). A disease affects cognitive processes. "The findings are consistent with the kinds of literature that RES has neuroprotective effects via decreasing the levels of IL-1β in many disease conditions including neuronal and cognitive diseases." (PMID 38058997, 2023).
Constipation (12 papers, 2018 to 2025). Infrequent or difficult evacuation of feces. "The increased mRNA levels of four cytokines, including tumor necrosis factor-α (TNF-α), interleukin (IL)-6, IL-4, and IL-1β, were remarkably recovered in Lop-induced constipation rats after treatment with MPC." (PMID 39857371, 2024). "The MODEL group exhibited significantly higher expression levels of both TNF-α and IL-1β compared to the CON group (p < 0.001), suggesting that constipation triggered an inflammatory reaction." (PMID 40806066, 2025). "The intestinal expression of IL-6, IL-1β, TNFα, PGE2, and COX-2 were increased in the constipation-induced group, whereas in the groups treated with HLp-nF1 or Dul, they were significantly decreased." (PMID 33872333, 2021). "Further study showed that BZYQD intervention reduced the levels of serum inflammatory factors IL-1β and TNF-α and colonic inflammatory factors IL-1β and IL-6 in constipation rats." (PMID 32317976, 2020). "An important factor in the pathogenesis of constipation is the dysfunction of intestinal immunoregulation, and pro-inflammatory factors (IL-1β, IL-6, IL-8, IFN-γ, TNF-α) and anti-inflammatory factor IL-10 are key indicators of the degree of inflammation in the constipation model." (PMID 40718808, 2025). "The levels of IL-1β and IL-6 mRNA were significantly higher in constipation patients (P < .05), while IL-8 mRNA level was no different between the 2 groups." (PMID 35960091, 2022). "Hence, these results provide evidence that SHP alleviates PTX-induced constipation and intestinal morphological damage but augments the effects of PTX on the expression of cytokines in the TLR4 pathway and IL-1β." (PMID 32733972, 2020).
endometrial cancer (12 papers, 2018 to 2025). Primary or metastatic malignant neoplasm involving the endometrium (mucous membrane that lines the endometrial cavity). "Moreover, NLRP10 is associated with a poor prognosis in endometrial cancer by inhibiting NF-κB activation and apoptosis, along with caspase-1-mediated IL-1β maturation." (PMID 40124684, 2025). "Estrogen has also been shown to enhance NLRP3, pro-IL-1β, and IL-1β expression, thereby promoting endometrial cancer progression through increased NLRP3 activation." (PMID 40718836, 2025). "The study discovered that estrogen activates the NLPR3 inflammasome, triggering increased expression of NLPR3, ERβ, pro‐IL‐1β, IL‐1β, and endometrial cancer cell proliferation." (PMID 37752941, 2023). "We observed LDH and IL-1β release to be increased in hydrogen-treated endometrial cancer cells that were upregulated by LPS and nigericin or downregulated by ROS, NLRP3, or the caspase-1 inhibitor." (PMID 31924176, 2020). "In contrast, overexpression of NLRP3 enhances the activities of proliferation, migration and invasion as well as increasing caspase-1 activation and IL-1β secretion in human endometrial cancer cells." (PMID 33613533, 2020). "We evaluated the information provided in articles published in English using a combination of keywords relevant to the proper adipokines, angiogenic growth factors (VEGF, FGF and IGF-1), inflammatory cytokines (TNFα, IL-6, IL-1β and IL-8) and endometrial cancer." (PMID 33799622, 2021). "In order to examine how BA affects the inflammatory responses in endometrial cancer, we initially assessed the concentrations of the pro-inflammatory cytokines TNF-α and IL-1β using immunofluorescence staining." (PMID 37772231, 2023). "Silencing NLPR3 inhibited tumor growth in a nude mouse endometrial tumor model, cell proliferation, migration, and invasion and reduced expression of IL-1β and caspase-1, while overexpression of NLPR3 led to the opposite results in endometrial cancer." (PMID 34239588, 2021). "Our data demonstrated that GSDMD was recruited to the NLRP3 inflammasome after LPS and nigericin priming in endometrial cancer cells, and that GSDMD was required for mediation by the NLRP3 inflammasome of pyroptosis and IL-1β production." (PMID 31924176, 2020). "Therefore, we hypothesize that GSDMD is the terminal protein in the pyroptotic sequence in endometrial cancer cells, and that GSDMD-mediated IL-1β secretion occurs via the ROS-NLRP3-caspase-1 signaling pathway is induced by activating effector molecular hydrogen." (PMID 31924176, 2020).
esophageal squamous cell carcinoma (12 papers, 2014 to 2025). Esophageal squamous cell carcinoma (ESCC) is a type of esophageal carcinoma (EC) that can affect any part of the esophagus, but is usually located in the upper or middle third. "As shown in previous studies, IL-6 and IL-1β are associated with the prognosis of esophageal SCC." (PMID 25238263, 2014). "M2 macrophages secrete pro-inflammatory cytokine IL-1β, which is correlated with the development of esophageal squamous cell carcinoma and is elevated in metabolic disorders." (PMID 40723226, 2025). "Among them, IL-1β can promote the migration and infiltration of esophageal squamous cell carcinoma cells, and increase the malignant cytological behavior of EC cells." (PMID 40606986, 2025). "Moreover, to evaluate the clinical significance of these findings, the predictive capacity of IL-1B regarding clinical outcomes and treatment responses in patients with esophageal SCC was assessed utilizing immunohistochemistry (IHC) analysis." (PMID 40141426, 2025). "IL-1β could enhance the invasion and migration of esophageal squamous cell carcinoma (ESCC) cells by promoting EMT and inducing the NF-ĸB signaling." (PMID 31492049, 2019). "T. forsythia can induce pro-inflammatory cytokines such as IL-1β and IL-6 by CD4 + T helper cells and TNF-α in esophageal squamous cell carcinoma (ESCC)." (PMID 35847109, 2022). "Some molecules involved in IL-1β/HBD-2 regulation, such as NFκB and MAPK, have been activated in esophageal SCC." (PMID 25226614, 2014). "Our studies found that the expression of IL-1β and FOXO3A was increased in esophageal squamous cell carcinoma (ESCC)." (PMID 38762529, 2024).
fibrosarcoma (12 papers, 2013 to 2025). A malignant mesenchymal fibroblastic neoplasm affecting the soft tissue and bone. "qRT-PCR revealed that the levels of mRNA for the proinflammatory cytokines Ifng, Il1b, and Il12b and the anti-inflammatory cytokine Il10 in fibrosarcomas induced by 5 μg MCA were similar in WT and CD155-deficient mice in both C57BL/6N and BALB/c backgrounds." (PMID 25384044, 2014). "We found that deficiency of IL-1β leads to delayed 3-MCA-induced fibrosarcoma development." (PMID 23847618, 2013). "In cancer, an enhanced accumulation of MDSCs, which facilitated tumor progression, was noted in mice with tumors derived from IL-1β-secreting fibrosarcoma cells and 4T1 cells." (PMID 30683126, 2019). "In a murine study, induced secretion of IL1β, one of the central mediators of acute infection, led to increased proliferation, migration, and invasion capacity of fibrosarcoma cells." (PMID 31906053, 2019). "We found that IL-1β- and ssIL-1β-transfected fibrosarcoma tumors were more invasive than the violent parental cells or mock-transfected cells." (PMID 23847618, 2013). "IL-1β had a slight inhibitory effect on fibrosarcoma, liposarcoma and synovial sarcoma MMP-2 and MMP-9 except for MMP-9 in synovial sarcoma which showed slight stimulation." (PMID 24085323, 2013). "Thus, fibrosarcoma cells that overexpress IL-1β have been shown to have increased invasive potential." (PMID 38248645, 2023). "Fibrosarcoma or Lewis lung carcinoma (LLC) cells modified to constitutively secrete IL-1β were shown in vivo to promote angiogenesis, through the induction of VEGF, CXCL2, and hepatocyte growth factor production by cancer and stromal cells, leading to tumor progression." (PMID 32635472, 2020). "No anti-tumor effector cells or cytokines that potentiate anti-tumor immunity (i.e., IFNγ and IL-2) could be detected in spleens of mice injected with fibrosarcoma cells transfected with IL-1β or ssIL-1β or with the violent parental cells." (PMID 23847618, 2013). "Moreover, IL-1β-overexpressing fibrosarcoma cells have an increased invasion potential." (PMID 32635472, 2020). "Thus, fibrosarcoma cells obtained from mice deficient in IL-1β failed to grow in WT mice, due to their inability to recruit a local inflammatory response that is essential for tumor invasiveness." (PMID 23847618, 2013). "The absence of IL-1β has been shown to inhibit the development of fibrosarcoma in murine models." (PMID 39744568, 2025).